MIR410 (microRNA 410)
Synonyms: hsa-mir-410; MIRN410; mir-410
Gene: MicroRNA gene on chromosome 14 (101,065,912 to 101,065,991, forward strand). Ensembl gene ENSG00000199092.
Gene Ontology:
Biological process: miRNA-mediated post-transcriptional gene silencing
Cellular component: RISC complex
Homologues: Orthologues: chimpanzee ptr-mir-410 (100% identical), guinea pig MIR410 (94% identical), mouse Mir410 (88% identical), rat Mir410 (88% identical). Paralogues in human: MIR323A (72% identical), MIR323B (70% identical), MIR487A (69% identical), MIR154 (66% identical), MIR496 (66% identical), MIR494 (64% identical), MIR382 (62% identical), MIR656 (62% identical), MIR539 (60% identical), MIR1185-1 (59% identical), MIR377 (58% identical), MIR409 (58% identical), and 4 more.
Diseases named in the same sentence as MIR410 in open-access papers:
MIR410 is named in the same sentence as 1 disease in open-access papers, as found by Europe PMC text mining. Sharing a sentence is not in itself a finding about the gene and the disease.
MIR410 shares sentences with these, for which no sentence is quoted: glioma (1 paper).